SPINT3 (serine peptidase inhibitor, Kunitz type 3)
Synonyms: HKIB9
Tractability: Antibody: UniProt places it where antibodies can reach, with high confidence; UniProt predicts a signal peptide or a membrane-spanning region; its Gene Ontology location is reachable by antibodies, with medium confidence.
Gene: Protein-coding gene on chromosome 20 (45,512,461 to 45,515,622, reverse strand). Ensembl gene ENSG00000101446.
Subcellular location: Secreted
Gene Ontology:
Molecular function: serine-type endopeptidase inhibitor activity
Cellular component: extracellular region
Genetic constraint (gnomAD): Loss-of-function variants: 4 observed, 3.57 expected, observed/expected ratio (o/e) 1.12, 90% interval 0.52 to 1.88. That is too few expected variants to judge how well the gene tolerates losing a copy. Missense variants: 97 observed, 108.39 expected, observed/expected ratio (o/e) 0.89, 90% interval 0.76 to 1.06. Synonymous variants: 30 observed, 40.21 expected, observed/expected ratio (o/e) 0.75, 90% interval 0.56 to 1.01.
Homologues: Orthologues: chimpanzee SPINT3 (96% identical), macaque SPINT3 (88% identical), rat Spint3 (49% identical), mouse Spint3 (43% identical).
Diseases named in the same sentence as SPINT3 in open-access papers:
SPINT3 is named in the same sentence as 3 diseases in open-access papers, as found by Europe PMC text mining. Sharing a sentence is not in itself a finding about the gene and the disease. The quoted sentences say what the papers report.
brain tumors (1 paper, 2023). "For the other identified candidate biomarkers (EDDM3B, LMOD1, GP2, SPINT3, CTRL, OXT) there is no specific literature linking them to gliomas or other brain tumors." (PMID 36959545, 2023).
glioma (1 paper, 2023). A benign or malignant brain and spinal cord tumor that arises from glial cells (astrocytes, oligodendrocytes, ependymal cells). "We identified 8 plasma proteins which were increased in gliomas vs. meningiomas (GFAP, NEFL, EDDM3B, PROK1, MMP3, CTRL, GP2, SPINT3) and 4 proteins which were decreased in gliomas vs. meningiomas (FABP4, ALDH3A1, IL-12B and OXT)." (PMID 36959545, 2023).
SPINT3 also shares sentences with these, for which no sentence is quoted: meningioma (1 paper).